MIR6859-1 (microRNA 6859-1)
Synonyms: hsa-mir-6859-1
Gene: MicroRNA gene on chromosome 1 (17,369 to 17,436, reverse strand). Ensembl gene ENSG00000278267.
Homologues: Paralogues in human: MIR6859-2 (100% identical), MIR6859-3 (100% identical), MIR6859-4 (100% identical).